MASTL (microtubule associated serine/threonine kinase like)
Diseases named in the same sentence as MASTL in open-access papers (continued):
Sharing a sentence is not in itself a finding about the gene and the disease.
cancer (continued). "Although MASTL (microtubule-associated serine/threonine kinase-like) is a key mitotic kinase that regulates mitotic progression through the inactivation of tumor suppressor protein phosphatase 2A (PP2A), the antitumor mechanism of MASTL targeting in cancer cells is still unclear." (PMID 29976159, 2018). "However, until recently, the role of MASTL in human diseases, such as cancer, were poorly understood." (PMID 30555827, 2018). "Notably, MASTL upregulation has been observed also in breast, colon, and other types of cancer." (PMID 36247015, 2022). "Inhibition of MASTL targets certain cancer types causing cell death, without harming normal cells." (PMID 29559668, 2018). "However, several recent studies suggest that MASTL may play several critical roles in cancer biology, including stimulating oncogenic AKT kinase activity, regulating normal DNA replication timing and recovery from pre-mitotic DNA damage checkpoint arrest." (PMID 29743597, 2018). "We analyzed the Cancer Cell Line Encyclopedia (CCLE) database for a potential connection between cisplatin resistance and the expression of MASTL and its downstream factors." (PMID 36247015, 2022). "These were selected based on previously reported functions that correlated with any of the known roles for MASTL (e.g., mitosis, EMT, cancer), the availability of commercial recombinant purified protein and those with the highest Log2 fold-change from our SILAC screen." (PMID 35732702, 2022). "MASTL inhibition selectively eradicated proliferative cancer cells rather than normal cells by inducing mitotic catastrophe." (PMID 34358073, 2021). "The AKT pathway contains multiple positive and negative feedback loops that are often disrupted in cancer, potentially explaining the differential correlation between MASTL overexpression and AKT activation." (PMID 30555827, 2018). "In this study, we delineated the MASTL-ENSA/ARPP19-PP2A/B55 pathway as an important determinant of cisplatin resistance and clinical treatment outcome in OSCC, and validated MASTL inhibition as a potentially valuable therapeutic strategy in combinatorial cancer therapy with cisplatin." (PMID 36247015, 2022). "Here we will discuss recent studies that support a role for MASTL independent of its kinase activity, outlining the dual functionalities and attempting to delineate the kinase-dependent and -independent roles during cancer progression." (PMID 32640605, 2020). "Yet, these results suggest that MASTL inhibition may contribute to the reactivation of PP2A in specific tumor types, an attractive possibility given the relevance of PP2A activation as a therapeutic strategy in cancer." (PMID 29229993, 2018). "Furthermore, many immunohistochemical or RNAseq datasets looking at the influence of MASTL on cancer progression have not considered the implications of MASTL isoforms, and this may be an area for future investigation or data mining." (PMID 32640605, 2020). "However, mitotic defects in MASTL-depleted cells can be partially rescued by depleting PP2A-B55 in human cancer cells, implying that PP2A-B55 is not the only substrate of the MASTL pathway." (PMID 38129815, 2023). "However, cancer progression is highly dependent on cell contractility and interactions with the ECM, both of which seem to be regulated by MASTL, independent of its kinase activity." (PMID 32640605, 2020).
tumor (18 papers, 2015 to 2025). "Taken together, our studies defined an important role of MASTL in conferring tumor cell resistance to cisplatin." (PMID 36247015, 2022). "By surveying previous studies that profiled gene expression in OSCC, we found significantly elevated expression of MASTL in tumor samples, in comparison to normal controls." (PMID 36247015, 2022). "These suggested that MASTL-mediated tumor progression was dependent on the tumor-suppressive action of PP2A, as PP2A dephosphorylates many oncogenic factors involved in the process of cellular transformation, such as c-Myc." (PMID 33117702, 2020). "For simplicity, we have limited the remainder of our review to the B55α subunit (herein referred to as B55), as it is a potential tumor suppressor and the primary target of MASTL in human cells." (PMID 30555827, 2018). "Our study provides support for the use of MASTL-specific inhibitors as tumor-selective drugs and in combination with radiotherapy through the promotion of mitotic catastrophe." (PMID 29976159, 2018). "Previous studies have shown that additional MASTL overexpression in MDA-MB-231 cells can promote primary tumour growth in mouse xenograft models." (PMID 29743597, 2018). "In the MASTL inducible knock out (isgMASTL) clone, transient treatment with doxycycline only for 1 week resulted in an initial reduction in tumor growth but this effect was lost after elimination of doxycycline." (PMID 29229993, 2018). "To analyze the effect of MASTL ablation on tumor growth we generated xenografts of the inducible MDA-MB-231 clones." (PMID 29229993, 2018). "To determine if inhibiting MASTL expression can similarly modulate colon tumorigenesis in vivo, we performed a subcutaneous xenograft tumor assay using HCT116MKD and respective control cells in athymic nude mice (n = 6/group)." (PMID 30068336, 2018). "In tumours, MASTL overexpression correlates with increased proliferation markers, however, in 2D cell culture we found that MASTL overexpression delayed interphase transit time and reduced cell proliferation." (PMID 29743597, 2018). "Given that the activity of the inducible CRISPR/Cas9 model is only partial, the difference in tumor growth between control and MASTL-null cells is possibly underestimated in these assays." (PMID 29229993, 2018). "Western blot analysis of the resected primary tumours confirmed that MASTL protein levels were significantly depleted upon Dox treatment in shMASTL cells." (PMID 29743597, 2018). "In vivo, overexpression of MASTL contributes to the growth of certain tumor cell lines in xenograft assays, whereas cells with MASTL knockdown display reduced growth in these assays." (PMID 29229993, 2018). "The proliferative function of MASTL in these tumor cells requires its kinase activity and the presence of PP2A-B55 complexes." (PMID 29229993, 2018). "The results from this assay likely underestimate the effect of MASTL ablation since a significant percentage of tumor cells maintain MASTL expression as a technical limitation of this genetic model." (PMID 29229993, 2018). "Using a new inducible CRISPR/Cas9 model in vivo we have shown that ablation of MASTL in tumors results in impaired tumor progression." (PMID 29229993, 2018). "Overexpression of MASTL at the protein level has been reported in several tumor types, yet its correlation with disease outcome was not deeply explored." (PMID 29229993, 2018). "MASTL targeting has reduced tumor growth in various in vitro and in vivo tumor models." (PMID 34358073, 2021). "Thus, inhibition of MASTL expression in these cells negatively affected their ability to grow in soft agar, invade through the matrix, and to induce tumor growth in vivo." (PMID 30068336, 2018).
tumor (continued). "Finally, we showed that knockdown of MASTL delayed primary tumour growth, and prevented invasion and metastasis of MDA-MB-231 cells, resulting in a significant increase in overall survival." (PMID 29743597, 2018). "However, the oncosuppressive mechanisms of MASTL targeting in tumor treatment and resistance are still unclear." (PMID 29976159, 2018). "A possible explanation is that increased amounts of both MASTL and ENSA could result in a larger pool of phosphorylated ENSA, inhibiting PP2A-B55 further and creating a functional loss of a tumor suppressor." (PMID 30555827, 2018). "Importantly, knockdown of MASTL resulted in a significant delay in tumour initiation and reduced tumour size, which resulted in an increase in overall survival, supporting previous reports that MASTL knockdown reduces primary tumour growth." (PMID 29743597, 2018). "At variance with other tumor types, TC shows neither overexpression nor mutations of MASTL." (PMID 31947935, 2020). "In addition, we previously showed that MASTL depletion inhibited radioresistant BCSCs, a key mediator of the radioresistance of tumor cells, indicating that MASTL inhibitors may be used as a radiosensitizer." (PMID 33117702, 2020). "Consequently, overexpression of MASTL could provide an oncogenic growth advantage by functionally repressing the tumor suppressor activity of PP2A-B55." (PMID 30555827, 2018). "Therefore, we wanted to determine if MASTL knockdown could affect both primary tumour growth and metastasis in vivo." (PMID 29743597, 2018). "In addition, high MASTL expression was also significantly correlated with increased Ki67 staining, suggested that MASTL may identify highly proliferative tumour cells." (PMID 29743597, 2018). "Specifically, PIWIL4, SATB1, GSE1, NCOR1, SAP30L, ATM, and BMI1 were significantly downregulated in tumor tissues relative to normal controls, while BUB1, CHEK1, MASTL, DNAJC2, UBE2D1, and SSRP1 showed pronounced upregulation." (PMID 41208974, 2025). "There is a clear enrichment for upregulation/amplification of MASTL-ENSA and a corresponding deletion or downregulation of PP2A-B55, matching their proposed oncogenic and tumor suppressor functions." (PMID 30555827, 2018). "In this review, we will examine the phenotypes and mechanisms for how MASTL, ENSA, and PP2A-B55 deregulation drives tumor progression and metastasis." (PMID 30555827, 2018). "Thereby, providing a logical explanation for the observed correlation between MASTL overexpression and increase in CIN in patient tumours." (PMID 29743597, 2018). "Overall these findings highlights the need of further investigation in order to assess whether MASTL may represent a useful target in different tumor types, as well as the search/design of strategies to block the activity of MASTL, for which no specific inhibitors have been so far identified." (PMID 26431489, 2015). "Notably, MASTL inhibition affects tumor cell but not normal primary fibroblast radiosensitivity, thus suggesting that MASTL could represent a druggable target to combine with radiotherapy." (PMID 26431489, 2015). "The dependency upon Cyclin D1, MASTL and COPZ1 activity is restricted to tumor cells and not normal thyroid cells, as previously reported for other tumor types." (PMID 26431489, 2015).
infection (2 papers, 2009 to 2018). The state of being infected such as from the introduction of a foreign agent such as serum, vaccine, antigenic substance or organism. "Parallel knock down (shRNA #8; shMASTL) and knock out (sgRNA #2; sgMASTL) assays elicited differential responses to MASTL depletion after lentiviral infection of a cell line panel with these sequences." (PMID 29229993, 2018).
MASTL also shares sentences with these, for which no sentence is quoted: melanoma (2 papers); cervical cancer (1); colon (1); colorectal adenocarcinoma (1); colorectal tumoral (1); endometrial tumors (1); esophageal cancer (1); low grade glioma (1); lung carcinoma (1); metabolic disorders (1); osteosarcoma (1); ovarian carcinoma (1); thrombocytopenia 2 (1); uveal melanoma (1); viral infection (1).